TLR5 (toll like receptor 5)
Description:
Pattern recognition receptor (PRR) located on the cell surface that participates in the activation of innate immunity and inflammatory response. Recognizes small molecular motifs named pathogen-associated molecular pattern (PAMPs) expressed by pathogens and microbe-associated molecular patterns (MAMPs) usually expressed by resident microbiota. Upon ligand binding such as bacterial flagellins, recruits intracellular adapter proteins MYD88 and TRIF leading to NF-kappa-B activation, cytokine secretion and induction of the inflammatory response. Plays thereby an important role in the relationship between the intestinal epithelium and enteric microbes and contributes to the gut microbiota composition throughout life (By similarity).
Synonyms: TIL3; FLJ10052; MGC126430; MGC126431; MELIOS; SLE1; SLEB1
Tractability: Small molecule: it belongs to a druggable protein family. Antibody: UniProt places it where antibodies can reach, with high confidence; its Gene Ontology location is reachable by antibodies, with high confidence; UniProt predicts a signal peptide or a membrane-spanning region. PROTAC: a small molecule that binds it is known. Other modalities: a drug acting on it is in phase 2 or 3 trials.
Target class: Toll-like and Il-1 receptors; Membrane receptor
Gene: Protein-coding gene on chromosome 1 (223,109,339 to 223,143,318, reverse strand). Ensembl gene ENSG00000187554.
Subcellular location: Cell membrane
Subcellular location (Human Protein Atlas): Golgi apparatus; Cytosol; Nucleoplasm
Pathways (Reactome):
Disease: IRAK4 deficiency (TLR5); MyD88 deficiency (TLR5)
Immune System: MyD88 cascade initiated on plasma membrane; Toll Like Receptor 5 (TLR5) Cascade
Gene Ontology:
Molecular function: interleukin-1 receptor binding; pattern recognition receptor activity; protein binding; signaling receptor activity; transmembrane signaling receptor activity
Biological process: cellular response to mechanical stimulus; positive regulation of interleukin-8 production; toll-like receptor 5 signaling pathway; inflammatory response; toll-like receptor signaling pathway; immune response; signal transduction
Cellular component: plasma membrane; membrane
Genetic constraint (gnomAD): Loss-of-function variants: 0 observed, 0.44 expected, observed/expected ratio (o/e) 0, 90% interval 0 to 1.85. That is too few expected variants to judge how well the gene tolerates losing a copy. Missense variants: 944 observed, 1,058 expected, observed/expected ratio (o/e) 0.89, 90% interval 0.85 to 0.94. Synonymous variants: 373 observed, 408.87 expected, observed/expected ratio (o/e) 0.91, 90% interval 0.84 to 0.99.
Homologues: Orthologues: chimpanzee TLR5 (99% identical), macaque TLR5 (92% identical), pig TLR5 (78% identical), mouse Tlr5 (72% identical), rat Tlr5 (70% identical), dog TLR5 (64% identical), tropical clawed frog tlrs5 (25% identical). Paralogues in human: TLR3 (23% identical), TLR8 (21% identical), TLR4 (20% identical), TLR7 (20% identical), TLR10 (18% identical), TLR1 (17% identical), TLR2 (17% identical), TLR6 (17% identical), LRRC32 (16% identical), IGFALS (15% identical), CD180 (15% identical), NRROS (15% identical), and 10 more.
Diseases named in the same sentence as TLR5 in open-access papers:
TLR5 is named in the same sentence as 260 diseases in open-access papers, as found by Europe PMC text mining. Sharing a sentence is not in itself a finding about the gene and the disease. The quoted sentences say what the papers report.
colitis (64 papers, 2010 to 2025). Inflammation of the colon. "TLR5, a Toll-like receptor recognizing bacterial flagellin, maintains microbial homeostasis and epithelial defense; its reduced expression in severe ulcerative colitis and spontaneous colitis in TLR5-deficient mice highlight its protective role." (PMID 41465205, 2025). "Several studies have shown that mice deficient in TLR5 were prone to developing spontaneous colitis." (PMID 38172943, 2024). "First, IL‐10‐, and TLR5 knock‐out mice developed immune‐based colitis associated with increased mucus layer permeability, suggesting a link between mucus properties and the immune system." (PMID 37691494, 2023). "Probably disruption of this mechanism is the explanation of the altered microbiota composition and increased susceptibility to the development of spontaneous colitis observed in TLR5−/− mice." (PMID 35049768, 2022). "Studies of another group indicated that deficiency of TLR5 altered the composition of the intestinal microbiota in comparison to the wild type mice, and low-grade inflammation and susceptibility to colitis were observed." (PMID 35049768, 2022). "In brief, the downregulation of TLR5 in IECs in the presence of disordered intestinal microbiota is a major cause of colitis, but R. intestinalis can induce an immune response by upregulating TLR5 expression through the production of butyrate." (PMID 35893896, 2022). "The mucus layers of epithelial TLR5-deficient mice were widely colonized by symbiotic microorganisms, resulting in spontaneous colitis (Burgueño and Abreu, 2020)." (PMID 35571126, 2022). "Various mouse models of colitis, including mice deficient in Muc2, Tlr5, Il10, or DSS-induced colitis model, had bacteria penetrating into the otherwise impenetrable inner colonic mucous layer." (PMID 34814945, 2021). "As an example, TLR5-deficient (T5KO) mice developed spontaneous colitis in part due to the inability to manage proteobacteria." (PMID 32466328, 2020). "Flagellin has been shown to have remarkable effects on a range of cell types, and changes in TLR5 are associated with both increased and decreased risk of many chronic diseases, including infection, colitis and cancer." (PMID 31133714, 2019). "Such an effect triggers colitis in animals deficient in either interleukin-10, a cytokine exerting anti-inflammatory and regulatory functions, or Toll-like receptor 5, a receptor recognizing the bacterial flagellin." (PMID 31581570, 2019). "Yet another experimental model of colitis where IL-10-deficiency facilitates IL-1β proinflammatory effects comes somewhat unexpectantly from studies of TLR5-deficient mice." (PMID 30455704, 2018). "A NEC-associated decrease in Tlr5 is consistent with TLR5 knockout mice developing spontaneous colitis (Refs 72, 73)." (PMID 27341512, 2016). "A genetic deficiency model using TLR5-/- mice that can develop spontaneous colitis showed that transient colonization by AIEC strain LF82 promoted the development of a colitic microbiota that persisted after AIEC was cleared by the host." (PMID 27711220, 2016). "A common feature of colitis-associated microbiota are increased levels of bioactive flagellin and lipopolysaccharide (LPS), which can activate Toll-like receptor 5 (TLR5), NOD-like Receptor 4 (NLRC4) inflammasome, and TLR4." (PMID 26867587, 2016). "Recently, in one study, a partial functional dominant negative of TLR5 was associated with protection against Crohn's disease; however the complete loss of TLR5(TLR5−/− mice) displays a high risk to develop colitis." (PMID 26090491, 2015). "Notably, spontaneous colitis induction in toll-like receptor (TLR)-5 and IL-10 knockout mice has been associated with an expansion of Proteobacteria." (PMID 35693794, 2022). "The Epsilonproteobacteria, which are an important food pathogen, contain flagella, which may activate TLR5 targets in early life and cause susceptibility to adult colitis." (PMID 33727402, 2021).
colitis (continued). "Moreover, they reported the development of colitis in animals deficient in either interleukin-10, a cytokine exerting anti-inflammatory and regulatory functions, or Toll-like receptor 5, a receptor recognizing the bacterial flagellin." (PMID 31581570, 2019). "Furthermore, this colitis was dependent on IL-1β generation since mice deficient in both TLR5 and IL-1R were protected from such induction of colitis." (PMID 30455704, 2018). "This microbial dysbiosis correlates with colitis severity, indicating the protective role of TLR5 against gut inflammation and in the maintenance of microbial homoeostasis." (PMID 40444793, 2025). "It has been recently reported that TLR5 KO mice display spontaneous colitis, which can induce metabolic syndrome, including hyperlipidemia, hypertension, insulin resistance, and obesity." (PMID 38167804, 2024). "Nevertheless, TLR-5 can be regulated by mechanisms other than flagellin induction, like IFN-γ, which downregulates TLR-5 after colitis induction in DSS models." (PMID 39683625, 2024). "In order to unequivocally specify the implications of TLR5 in DVF-induced exacerbation of DSS colitis, Tlr5−/− mice were generated and were stimulated by DVF or not." (PMID 38172943, 2024). "In the present study, the levels of IL-6, IL-17A, IL-1β, and TNF-α were increased, accompanied by increased expression of TLR5/MyD88/NF-κB pathway in TNBS induced colitis rats." (PMID 35571126, 2022). "We found that R. intestinalis significantly upregulated the transcription of TLR5 in intestinal epithelial cells (IECs) and improved colonic inflammation in a colitis mouse model." (PMID 35893896, 2022). "The semi-quantitative analysis confirmed that in the TNBS-induced colitis group, there were substantial reductions in TLR5 protein levels; however, these were restored in the SBP group (5.9 g/kg) and MES group (p < 0.01, p < 0.05)." (PMID 35571126, 2022). "To explore the protective mechanism of SBP on TNBS-induced colitis, we detected the protein expression of TLR5 in the colon." (PMID 35571126, 2022). "WB and immunofluorescence experiments confirmed that the expression levels of MMP-9, PTGDS, SLC26A8, and CD160 in colitis were significantly increased, whereas that of TLR5 were decreased." (PMID 36733384, 2022). "The expression of TLR5 was reduced in colitis mice, whereas the expression was increased after treatment with R. intestinalis." (PMID 35893896, 2022). "In this study, we further investigate the relationship between the destruction of the MUC2-related mucus barrier and the colonic inflammation triggered by the TLR5/MyD88/NF-κB pathway in the TNBS-induced colitis model." (PMID 35571126, 2022). "Rather, as evidenced by the tendency of TLR5 knockout mice to develop colitis, flagellin contributes to negatively regulating the response to gut microbiota via IL-10 production and by stimulating regulatory CD4+ T cells." (PMID 36555214, 2022). "In this study, we investigated the role of R. intestinalis and Toll-like receptor 5 (TLR5) in relieving mouse colitis." (PMID 35893896, 2022). "Conditional deletion of toll-like receptor 5 (Tlr5) from intestinal epithelial cells shows low-grade inflammation, metabolic syndrome, and colitis as compared to wild-type littermates." (PMID 34159422, 2021). "Emodin was found to protect mice from DSS-induced colitis via the regulation of TLR5/NF-κB signaling pathway, and significantly inhibit LPS-mediated NF-κB activation and DNA binding activity in RAW264.7 cells." (PMID 33432986, 2021). "It was shown that in DSS and TNBS- induced model of colitis, Notch ligands and receptors were upregulated in colonic epithelial cells in a TLR5 -dependent manner." (PMID 34336718, 2021). "Since the flagellum and its constituent protein flagellin are recognized by host TLR5, we performed DSS-induced colitis experiments using TLR5-deficient (Tlr5−/−) mice." (PMID 31206517, 2019).
colitis (continued). "TLR5−/− mice develop a spontaneous colitis and mice treated with purified Salmonella-derived flagellin as a TLR5 agonist are protected from Clostridium difficile colitis." (PMID 29515999, 2018). "The use of a third model of colitis with TLR5−/− mice, which also develop chronic colitis, permitted the comparison between two models of chronic colitis with different origin and severities." (PMID 28566745, 2017). "Analysis of the expression levels of the nine-miRNA panel revealed that three miRNAs (miR-122-5p, miR-150-5p, and miR-375) were similarly altered (all up-regulated) in mice with DSS-induced and TLR5−/− colitis compared to the corresponding healthy controls." (PMID 28566745, 2017). "These bacteria are capable of flagellin/TLR5 signaling, which is important for host defense and disease protection, because deletion of TLR5 results in colitis." (PMID 29018440, 2017). "In experimental animals, TLR5 deficient mice have been demonstrated to develop spontaneous colitis, supporting the suggested protective role of TLR5 in humans." (PMID 25821356, 2015). "Tlr5−/− mice develop spontaneous colitis, despite an increased number of Foxp3+ Tregs compared to WT littermates." (PMID 26583115, 2015). "C3H/HeJBir mice, a substrain which develops spontaneous colitis, were used to identify a family of related novel flagellins, which activate TLR5, as a class of immunodominant antigens." (PMID 26583115, 2015). "TLR-2, TLR-4, and TLR-5 knockout mice, though not to the same extent as MyD88−/− mice, have a reduced capacity to repair colonic mucosa and reduced barrier function, with TLR5 knockout mice developing spontaneous colitis." (PMID 25377316, 2015). "Further support for a potential role for TLR5 comes from recent observations that flagellins such as CBir1 are also dominant antigens in different models of experimental colitis." (PMID 23593463, 2013). "While TLR2 and TLR4 were up-regulated, TLR5 was significantly down-regulated in our TNBS-colitis model." (PMID 23382912, 2013). "Our results reveal for the first time that the induction of colitis or ileitis in mice is associated with marked increases in the luminal concentrations of PAMPs specific for TLR2, TLR4 and/or TLR5." (PMID 20161736, 2010). "In addition, R. intestinalis produces butyrate that inhibits colitis by increasing the expression of the TLR5 gene, and its flagellin induces the immune response and promotes the release of anti-inflammatory factors." (PMID 40822850, 2025). "Screening of disease markers for colitis in mice using a machine-learning approach revealed that the expression levels of SLC26A8, MMP9, PTGDS, and CD160 were significantly elevated in colitis tissues, whereas the expression level of TLR5 was significantly reduced." (PMID 40110435, 2025). "Further support for this hypothesis comes from our in vivo and in vitro experiments, in which the expression levels of TLR5 was not increased after DVF stimulation and DVF significantly worsened the severity of DSS-induced colitis in Tlr5−/− mice." (PMID 38172943, 2024). "Moreover, TLR2-, TLR5- and TLR9-deficient mice are also more susceptible to chemically induced colitis." (PMID 36982420, 2023). "Moreover, TLR5 is essential for maintaining gastrointestinal health, as suggested by the inability to manage commensal microbiota and the development of spontaneous colitis with the loss of IEC-specific TLR5 and TLR5-mediated gene expression in mice." (PMID 35893896, 2022). "The destruction of this mechanism might explain why the mucous layers of TLR5-/- and epithelial MUC2-deficient mice are more colonized by symbiotic microorganisms, resulting in the eventual development of spontaneous colitis." (PMID 35571126, 2022). "Additionally, butyrate produced by R. intestinalis can further increase the expression of the TLR5 gene and inhibit colitis." (PMID 35893896, 2022). "TLR5 (Toll-like receptor 5) knockout mice may serve as a model of colitis that is dependent on the presence of microbiota." (PMID 36140740, 2022).
colitis (continued). "Therefore, we concluded that the beneficial effects of symbiotic EcN on the progress and outcome of DSS-induced colitis is mainly mediated by the interaction of host TLR5 with EcN flagella." (PMID 31206517, 2019). "A flagellum renders bacteria motile, but this study reveals another property important for symbiosis: the hypervariable region of Escherichia coli flagellin strongly determines activation of TLR5, mediating benefits for the host such as protection against colitis." (PMID 31206517, 2019). "However, flagellin enemas have been shown to exacerbate established DSS colitis although in a non-TLR5-dependent manner, highlighting the need for further studies." (PMID 29515999, 2018). "A closer look on other colitis models showed that the signature can also be used to distinguish across the various models: between TLR5−/− (green) and DSS D7 (orange) mice, between IL10−/− D98 mice (after colitis, red) and TLR5−/− mice (green) and between DSS D7 (orange) and IL10−/− D98 mice." (PMID 28566745, 2017). "Also, Proteobacteria can be selected (over Bacteroidetes and Firmicutes) by intestinal inflammation as tested by TLR5-knockout mice, and some Proteobacteria can induce colitis in this background, potentially leading to a feedback loop." (PMID 28330508, 2017). "Furthermore, TLR5 knockout mice are prone to spontaneous colitis; in contrast, TLR5 overactivation can negatively regulate some inflammatory bowel diseases, such as Crohn's disease and ulcerative colitis." (PMID 25283154, 2014). "For example, the development of spontaneous intestinal inflammation has been reported in TLR5 knockout (KO) mice, with around 35–40% of these mice presenting with colitis and exhibiting areas of extensive mononuclear infiltration, epithelial hyperplasia, and focal epithelial crypt destruction." (PMID 24062746, 2013). "The decrease could be explained by the phenotype of Tlr5−/− mice, which are known to develop spontaneous colitis." (PMID 23785460, 2013). "Activation of the TLR5 pathway also appears to be the mechanism by which adherent-invasive Escherichia coli (AIEC) exacerbates inflammation in dextran sulfate sodium (DSS)-induced colitis." (PMID 24062746, 2013). "Indeed, it has been shown that TLR5 knockout mice have more severe gut pathology and develop spontaneous colitis." (PMID 22279566, 2012). "TLR5 knockout mice develop spontaneous colitis and exhibit decreased intestinal expression of TLR5." (PMID 21203467, 2010). "Moreover, R. intestinalis’ butyrate synthesis boosted TLR5 gene expression and reduced colitis." (PMID 38685971, 2024). "The mechanism of SBP improving colitis may be related to the inhibition of TLR5 and its associated inflammatory pathways even it did not achieve a positive dose-effect relationship." (PMID 35571126, 2022). "However, mice without TLR5 express mosaic phenotype, with a subset of mice that shows increased susceptibility to the spontaneous colitis development and lack of the normal, double structure of colon mucus layer." (PMID 35049768, 2022). "Moreover, studies in a murine model of IBD suggest that TLR5 signalling could play a protective role in IBD as TLR5 knockout mice develop spontaneous colitis." (PMID 22279566, 2012). "Interestingly, TLR5 activation by flagellin has been shown not to cause inflammation in normal animals but to enhance the changes associated with DSS colitis." (PMID 21647408, 2011). "Moreover, deletion of TLR4 rescued the colitis in these TLR5 knockout mice." (PMID 21203467, 2010). "Flagellin from E. coli Nissle 1917 activates TLR5, significantly increases IL-22 production, and prevents DSS-induced colitis." (PMID 40444793, 2025). "The expression of MMP-9, PTGDS, SLC26A8, and CD160 in colitis was increased in the IBD mouse model, whereas the expression of TLR5 was downregulated." (PMID 36733384, 2022).